EPDR1 (ependymin related 1)
Description:
Binds anionic lipids and gangliosides at acidic pH.
Synonyms: MERP-1; MERP1; UCC1; EPDR
Tractability: Antibody: UniProt places it where antibodies can reach, with high confidence; its Gene Ontology location is reachable by antibodies, with high confidence; UniProt predicts a signal peptide or a membrane-spanning region. PROTAC: its protein half-life has been measured.
Gene: Protein-coding gene on chromosome 7 (37,920,640 to 37,951,936, forward strand). Ensembl gene ENSG00000086289.
Subcellular location: Lysosome lumen; Secreted
Gene Ontology:
Molecular function: ganglioside GM1 binding; identical protein binding; phospholipid binding; protein binding; calcium ion binding
Biological process: myofibroblast contraction; cell-matrix adhesion
Cellular component: extracellular region; lysosomal lumen; lysosome
Genetic constraint (gnomAD): Loss-of-function variants: 30 observed, 24.97 expected, observed/expected ratio (o/e) 1.2, 90% interval 0.9 to 1.63. The synonymous counts are far from expectation, so gnomAD's model fits this gene poorly and the ratio says little. Missense variants: 349 observed, 271.64 expected, observed/expected ratio (o/e) 1.28, 90% interval 1.18 to 1.4. Synonymous variants: 137 observed, 106.31 expected, observed/expected ratio (o/e) 1.29, 90% interval 1.12 to 1.49.
Homologues: Orthologues: chimpanzee EPDR1 (99% identical), macaque EPDR1 (96% identical), pig EPDR1 (87% identical), rabbit EPDR1 (85% identical), dog EPDR1 (83% identical), guinea pig EPDR1 (82% identical), rat Epdr1 (81% identical), mouse Epdr1 (79% identical), tropical clawed frog epdr1 (56% identical), zebrafish epdr1 (53% identical), zebrafish epdl2 (26% identical), zebrafish epdl1 (21% identical), and 1 more.
Diseases named in the same sentence as EPDR1 in open-access papers:
EPDR1 is named in the same sentence as 29 diseases in open-access papers, as found by Europe PMC text mining. Sharing a sentence is not in itself a finding about the gene and the disease. The quoted sentences say what the papers report.
colorectal cancer (11 papers, 2017 to 2024). A primary or metastatic malignant neoplasm that affects the colon or rectum. "Although EPDR1 has been studied in colorectal cancer and is considered a protumor molecule capable of accelerating tumor metastasis, its function remains controversial, and the specific mechanism underlying its actions is yet to be fully elucidated." (PMID 39152265, 2024). "At present, EPDR1 has been reported to be differentially expressed in a variety of tumors and exerts an oncogenic role in colorectal cancer and a tumor-suppressive role in breast cancer." (PMID 35004274, 2021). "Similarly, a study by F. Gimeno-Valiente showed that the expression of EPDR1 was upregulated in 101 colorectal cancer (CRC) patients in a prospective cohort, and they found that a high level of EPDR1 expression is associated with T and M parameters in CRC." (PMID 36276104, 2022). "One study on colorectal carcinoma demonstrated that DNA methylation might play a critical role in EPDR1 expression‐regulation." (PMID 32935479, 2020). "Lately, several studies were reported that EPDR1 was closely related to pathological or developmental processes of various tumors including breast cancer (BRCA), hepatocellular carcinoma (HCC), colorectal cancer, and so on." (PMID 33902536, 2021).
hepatocellular carcinoma (7 papers, 2020 to 2025). A malignant tumor that arises from hepatocytes. "Aberrant expression of EPDR1 in hepatocellular carcinoma is associated with immunosuppression." (PMID 39152265, 2024). "In hepatocellular carcinoma, ependymin-related protein 1 (EPDR1) is an important tumor-intrinsic regulator of PD-L1 expression and tumor immune evasion." (PMID 41035656, 2025). "For example, ependymin-related protein 1 (EPDR1) overexpression in hepatocellular carcinoma leads to cancer immune suppression." (PMID 39851497, 2025). "In several other works in the literature, the gene expression profile of EPDR1 was also elevated in other cancers, such as hepatocellular carcinoma, pancreatic adenocarcinoma, and stomach adenocarcinoma." (PMID 36276104, 2022). "Our study reported that EPDR1 correlates with immune cell infiltration and can be used as a prognostic biomarker in hepatocellular carcinoma." (PMID 32935479, 2020). "This study identifies ependymin-related protein 1 (EPDR1) as a potent regulator of PD-L1 expression in hepatocellular carcinoma (HCC), facilitating immune evasion." (PMID 39152265, 2024). "In hepatocellular carcinoma (HCC), ependymin-related protein 1 (EPDR1) plays a regulatory role on PD-L1 expression to mediate immune evasion in a TRIM21-dependent manner." (PMID 40735642, 2025). "EPDR1 inhibits TRIM21/NF-κB interaction, stabilizes NF-κB-mediated transcriptional upregulation of PD-L1 in hepatocellular carcinoma cells, and inhibits immune response." (PMID 39851497, 2025).
bladder cancer (5 papers, 2021 to 2024). "A study revealed that EPDR1 had increased expression levels in bladder cancer tissues, which were associated with poorer survival results." (PMID 38162504, 2023). "In our study, we found that the expression of EPDR1 in tumor tissues was significantly associated with the grade, metastasis, invasion, and survival of bladder cancer." (PMID 36276104, 2022). "Finally, we attempted to quantify the risk of differential EPDR1 expression and tumor budding with a predictive model for bladder cancer patients." (PMID 36276104, 2022). "In this study, we found that bladder cancer patients had shorter survival rates, and higher expression of EPDR1 and higher positivity for TB were detected in MIBC tumor tissues when compared with NMIBC." (PMID 36276104, 2022). "In this study, we focused on the pathological features of EPDR1 and tumor budding and further investigated the potential clinical prognosis of EPDR1 and the survival of bladder cancer patients." (PMID 36276104, 2022). "EPDR1 was highly expressed in bladder cancer patients with high tumor stages (pT), wider metastases, and positive lymph nodes, all of which indicate a worse prognosis." (PMID 36276104, 2022). "In conclusion, bladder cancer patients with higher expression levels of EPDR1 had worse survival outcomes." (PMID 36276104, 2022). "In our previous study, we found that EPDR1 expression was significantly related to different grades and metastases in bladder carcinoma patients." (PMID 36276104, 2022). "In our present study, we aimed to explore the differential expression of EPDR1 protein in the pathology of graded bladder carcinoma and found a relationship between various expression levels of EPDR1 and TB and the prognosis of MIBC patients." (PMID 36276104, 2022). "Therefore, we collected a large number of bladder carcinoma tumor tissues to explore and confirm the significance of EPDR1 in bladder carcinoma." (PMID 36276104, 2022). "Moreover, we used “tumor budding”, an emerging prognostic biomarker in solid cancers, to assist EPDR1 in predicting the prognosis of bladder carcinoma." (PMID 36276104, 2022). "Ultimately, EPDR1 may be an actionable target in bladder cancer." (PMID 36276104, 2022). "Furthermore, we found that EPDR1 and tumor budding could be crucial factors for affecting the prognosis of bladder carcinoma, even better than pTMN(Riskscore=(0.724)* pT_stage +(4.960) *EPDR1+(4.312)*TB)." (PMID 36276104, 2022). "Thus, we speculated that EPDR1 could affect the progression and metastasis of bladder cancer." (PMID 36276104, 2022).
breast carcinoma (3 papers, 2021 to 2024). "Consistent with the results observed in breast cancer, our data indicated that EPDR1 was downregulated in EOC tissues and low expression of EPDR1 was associated with poor prognosis." (PMID 35004274, 2021). "EPDR1 mRNA expression presents an impairment in breast cancer, and breast cancer cells containing overexpressed EPDR1 are characterized by suppressed cell activities." (PMID 34218800, 2021). "However, our study only examined the effect of EPDR1 expression on the expression of interstitial-related proteins in breast cancer, and comprehensive studies are needed to confirm the direct link between EPDR1 overexpression and EMT inhibition." (PMID 38308220, 2024). "EPDR1 is commonly regarded to suppress tumor growth in human cancers, such as breast cancer." (PMID 34218800, 2021). "However, it has been proven that EPDR1 exhibited a lower expression level in breast cancer tissues compared to adjacent normal tissues and functioned as a tumor suppressor in breast cancer cells." (PMID 35004274, 2021).
Obesity (3 papers, 2024 to 2025). Accumulation of substantial excess body fat. "Lastly, our study is cross‐sectional and does not establish a causal relationship between increased circulating EPDR1 levels and the occurrence and development of obesity." (PMID 40626250, 2024). "Our findings showed that the relative risk of obesity increased significantly with increasing EPDR1 levels." (PMID 40626250, 2024). "Nevertheless, our data provide clinical evidence suggesting that elevated serum EPDR1 may be linked to metabolic disorders and may have a potential role in the pathogenesis of obesity." (PMID 40626250, 2024). "In summary, our data provides clinical evidence that elevated serum EPDR1 may play a potential role in the development of obesity and may be associated with metabolic disorders." (PMID 40626250, 2024). "EPDR1 is strongly associated with obesity and may also be associated with metabolic disorders." (PMID 40626250, 2024). "Therefore, the concentration of serum EPDR1 may serve as a biomarker for predicting the risk of obesity." (PMID 40626250, 2024). "To further investigate the relationship between EPDR1 and obesity, we divided serum EPDR1 levels into four quartiles based on its concentration in the entire cohort (Q1, <166.0 μg/ml; Q2, 166.0–201.0 μg/ml; Q3, 201.0–276.0 μg/ml, and Q4, >276.0 μg/ml)." (PMID 40626250, 2024). "To further clarify the relationship between EPDR1 and obesity, we conducted ROC curve analysis of serum EPDR1 levels to predict obesity." (PMID 40626250, 2024). "To investigate the relationship between EPDR1 and obesity further, we analyzed the prevalence of obesity across different quartiles of circulating EPDR1 levels." (PMID 40626250, 2024). "Our findings showed that serum EPDR1 levels were significantly elevated in children with obesity compared to those with normal weight." (PMID 40626250, 2024). "EPDR1, another adipokine, is important in the emergence of obesity and metabolic disorders." (PMID 40642507, 2025). "We speculate that the high levels of EPDR1 in patients with obesity may be related to BMI and inflammatory status but further studies with larger sample sizes are needed to confirm these preliminary findings." (PMID 40626250, 2024). "The aim of this study was to investigate serum EPDR1 levels in children with obesity and normal‐weight children and to compare the levels of EPDR1 between children with obesity, with and without metabolic‐associated fatty liver disease (MAFLD)." (PMID 40626250, 2024). "Finally, we assessed the correlation between serum EPDR1 and obesity using ROC curves, which revealed that circulating EPDR1 could serve as a valuable marker for predicting obesity." (PMID 40626250, 2024). "Of note, EPDR1 is also found in β-cells, whose expression was elevated in individuals with T2D and obesity, although the relative contributions of BAT-derived vs islet-derived EPDR1 remain to be clarified." (PMID 40658727, 2025).
ovarian carcinoma (3 papers, 2021 to 2024). A malignant neoplasm originating from the surface ovarian epithelium. "This research was to decipher the mechanism of long non-coding RNA SDCBP2-AS1 in ovarian cancer (OC) through regulation of microRNA (miR)-100-5p and ependymin-related protein 1 (EPDR1)." (PMID 34218800, 2021). "Taken together, these results confirmed that EPDR1 played the role of a tumor suppressor gene in ovarian cancer through inhibiting the PI3K/AKT pathway and the process of EMT." (PMID 35004274, 2021). "In contrast, EPDR1 exerts inhibitory effects in ovarian cancer and BC." (PMID 38308220, 2024). "We first detected the expression of EPDR1 in various ovarian cancer cell lines." (PMID 35004274, 2021).
asthma (2 papers, 2017 to 2020). "Additionally, expression of ependymin-related protein 1 (Epdr1; previously termed Merp2) was monitored, because it was downregulated in a murine asthma model; whereas Tff1 was upregulated in this model." (PMID 31963721, 2020). "Furthermore, the expression of ependymin related protein 1 (Epdr1, previously termed Merp2) was monitored, because it was downregulated in a murine asthma model." (PMID 28604600, 2017).
colon cancer (2 papers, 2019 to 2021). "Tumour-suppressor genes (MLH1 and RUBCNL), protooncogene (AGR2), and genes reported to be linked with colon cancer (EPDR1, MLH1, AXIN2) were enriched in the signature." (PMID 31008109, 2019).
Insulin resistance (2 papers, 2022 to 2025). Increased resistance towards insulin, that is, diminished effectiveness of insulin in reducing blood glucose levels. "Similar to this, increased PSAP and EPDR1 levels in the serum may be predicted by higher degrees of insulin resistance." (PMID 40642507, 2025). "Therefore, increased serum PSAP and EPDR1 levels in T2DM participants suggest increased blood insulin resistance levels." (PMID 40642507, 2025). "The levels of PSAP and EPDR1 may be used as possible biomarkers to predict the emergence of insulin resistance and T2DM." (PMID 40642507, 2025). "Therefore, we conducted this cross-sectional study to assess the levels of the peptides PSAP and EPDR1 in the blood of individuals with T2DM, as well as investigate any potential associations between these peptide levels and markers of insulin resistance among the subjects." (PMID 40642507, 2025). "Taken together, blood levels of EPDR1 and PSAP were considerably greater in T2DM patients compared to healthy controls and were correlated with enhanced insulin resistance levels." (PMID 40642507, 2025). "Taken together, these results suggest important therapeutic implications for EPDR1 and the TGF-β pathways in pathologic angiogenesis during hyperinsulinemia and insulin resistance." (PMID 35872017, 2022).
colorectal adenocarcinoma (1 paper, 2018). The most common type of colorectal carcinoma. "Similarly, a negative correlation between mRNA expression and DNA methylation of the EPDR1 gene in 195 colorectal adenocarcinoma patients was reported in The Cancer Genome Atlas (TCGA) dataset." (PMID 30360391, 2018).
Dupuytren's disease (1 paper, 2023). "We find that the strongest risk factor inherited from Neandertals is associated with altered splicing of EPDR1 transcripts in 3 tissues relevant for Dupuytren's disease; muscle (P = 1.7 × 10−23), adipose tissue (P = 1.1 × 10−11), and cultured fibroblasts (P = 5.9 × 10−8; fig." (PMID 37315093, 2023). "Although the exact pathophysiological mechanism for how the truncation of EPDR1 might contribute to the development of Dupuytren's disease deserves further investigation, it is worth noting that this protein is suggested to be involved in myofibroblast contractility." (PMID 37315093, 2023).
ependymoma (1 paper, 2022). A WHO grade II, slow growing tumor of children and young adults, usually located intraventricularly. "The EPDR1 (ependymin-related 1) gene produces a type II transmembrane protein that is related to the protocadherins and ependymoma, two families of cell-adhesion molecules." (PMID 36360315, 2022).
epilepsy (1 paper, 2024). A brain disorder characterized by episodes of abnormally increased neuronal discharge resulting in transient episodes of sensory or motor neurological dysfunction, or psychic dysfunction. "The CFA14 risk haplotype was associated with upregulation of CLIC1, ACE2, and PIGN and downregulation of EPDR1, all known to be involved with epilepsy or the Wnt/β-catenin signaling pathway." (PMID 39596674, 2024).
liver cancer (1 paper, 2024). An epithelial or non-epithelial malignant neoplasm that arises from the liver. "Moreover, the expression of EPDR1 was significantly associated with reduced five-year survival rates in liver cancer patients (Fig. EV1B)." (PMID 39152265, 2024). "Analysis of samples from the liver cancer mouse model confirmed the positive correlation of EPDR1 and PD-L1 at the protein level (Fig. EV5B)." (PMID 39152265, 2024). "Analysis of the TCGA liver cancer dataset revealed a significant increase in EPDR1 expression in malignant tissue compared to healthy tissue (Fig. EV1A)." (PMID 39152265, 2024). "By employing a xenograft model generated by subcutaneous inoculation with murine liver cancer cell Hepa 1–6 expressing shEPDR1, we unveiled that suppression of EPDR1 led to a decrease in xenograft proliferation (Fig. EV2G–I)." (PMID 39152265, 2024). "Further, we validated through a mouse liver cancer model that EPDR1 mediates exhaustion of CD8+ T cells and promotes tumor progression." (PMID 39152265, 2024). "Our findings revealed the protumor role of EPDR1 in liver cancer and elucidated its modulation of PD-L1 and antitumor immunity for the first time." (PMID 39152265, 2024). "In addition, we observed a positive correlation between EPDR1 and PD-L1 expression in both human and mouse liver cancer samples." (PMID 39152265, 2024). "In this study, we set out to search for potential targets for liver cancer ICB treatment and find an unappreciated role for EPDR1 in regulating cancer progression and immune evasion." (PMID 39152265, 2024). "To investigate the impact of EPDR1 on tumor immunity, we employed a YAP5SA-induced mouse liver cancer model." (PMID 39152265, 2024). "To evaluate the effect of EPDR1 on the in vivo growth of liver cancer, we utilized an HCC mice model established by subcutaneous injection of Hepa 1–6 murine liver cancer cells expressing Flag-tag empty vector (Flag-EV) or murine EPDR1 (Flag-mEPDR1)." (PMID 39152265, 2024). "Thus, targeting EPDR1 and TRIM21 holds promise as a novel strategy for improving liver cancer immunotherapy." (PMID 39152265, 2024).
myeloma (1 paper, 2015). "Notably, six of the top deregulated genes (NUDT11, PKP2, ROBO1, AGAP1, NAP1L3 and EPDR1) were recently identified as “stem cell” genes in myeloma." (PMID 24913504, 2015). "It is also noteworthy that the 37 top deregulated genes were enriched for the myeloma “stem cell” gene set, including NUDT11, PKP2, ROBO1, AGAP1, NAP1L3 and EPDR1, indicating that “stemness” may play an important role in determining high risk behavior." (PMID 24913504, 2015).